GLP1R (glucagon like peptide 1 receptor)
Diseases named in the same sentence as GLP1R in open-access papers (continued):
Sharing a sentence is not in itself a finding about the gene and the disease.
diabetes (continued). "Clinical trials have tested the effects of GLP-1R agonists in patients with PD, AD, or diabetes-related memory impairment, showing significant improvement in these patients’ conditions." (PMID 39719978, 2024). "In this review, we aim to summarize the potential beneficial effects of GLP-1R agonists beyond their established roles in diabetes and obesity management." (PMID 39858999, 2024). "Glucagon-like peptide-1 receptor agonists are medications widely used for treating obesity and diabetes." (PMID 39796706, 2024). "In fact, several GCGR/GLP-1R dual agonists are currently undergoing clinical trials for the treatment of diabetes, obesity, and nonalcoholic steatohepatitis." (PMID 38879678, 2024). "Glucagon-like peptide 1 receptor agonists have been proven to be effective in adults with diabetes and children with obesity." (PMID 38659064, 2024). "This diabetes drug acts as a dual agonist for GLP1R and the glucose-dependent insulinotropic polypeptide (GIP) in humans but acts as a potent GLP1R agonist in rodents." (PMID 39007271, 2024). "So far, we have proven that daphnetin mitigated diabetes cognitive dysfunction, inhibited oxidative stress and inflammation, and GLP-1R is a key regulatory factor." (PMID 39257395, 2024). "Glucagon-like peptide-1 receptor (GLP-1R) agonists have garnered significant attention for their therapeutic potential in addressing the interconnected health challenges of diabetes, obesity, and cancer." (PMID 38801466, 2024). "Glucagon-like peptide-1 receptor (GLP-1R) agonists have been approved for the management of diabetes due to their effect on glucose homeostasis and satiety regulation." (PMID 39148946, 2024). "A recent study showed a lower risk association of semaglutide with suicidal ideation compared to non-GLP1R agonist anti-obesity and anti-diabetes medications." (PMID 39015186, 2024). "GLP-1R and GLP-1R agonists are already approved for type-2 diabetes mellitus (T2DM) and obesity treatment." (PMID 38542187, 2024). "Glucagon-like peptide-1 receptor agonists (GLP-1 RAs) were initially approved for improvement of metabolic control in patients living with diabetes." (PMID 38846069, 2024). "GLP-1R agonists become research hotspot in diabetes-related medicine field and are used in the development of targeted drugs for diabetes." (PMID 39257395, 2024). "That said, as with GIPR agonism, it is clear that the metabolic advantages of sustained GIPR antagonism in obesity and obesity-driven forms of diabetes can be enhanced by concurrent GLP-1 receptor (GLP-1R) activation." (PMID 38861364, 2024). "While GLP-1R agonists offer significant benefits in diabetes and obesity management, their complex effects on calcium homeostasis necessitate careful patient monitoring and individualized treatment approaches." (PMID 39201039, 2024). "The diabetes medications included metformin (n = 11), sulfonylurea (n = 6), insulin (n = 5), glucagon-like peptide 1 receptor agonists (GLP-1RA) (n = 4), and gliptins (n = 3)." (PMID 39381685, 2024). "Since GLP-1R is a target in diabetes mellitus, it enhances the proliferation of β-cells and insulin secretion in the pancreas and reduces plasma glucose levels." (PMID 38801466, 2024). "Liraglutide is an agonist of GLP-1R, which is primarily used for the treatment of type 2 diabetes mellitus, and administered by subcutaneous injection once daily." (PMID 38438663, 2024). "In clinical practice, GLP‐1 receptor (GLP‐1R) agonists are used as medications to treat diabetes by enhancing GLP‐1R signalling and promoting insulin release from pancreatic islets." (PMID 38926763, 2024). "Semaglutide, like many other GLP-1R agonists, is used in diabetes and obesity to decrease glucose levels and manage body weight, which plays a role in tumorigenesis." (PMID 38801466, 2024). "Glucagon-like peptide-1 receptor agonists (GLP-1RAs) are gaining popularity in the management of diabetes mellitus and obesity." (PMID 39238749, 2024).
diabetes (continued). "Despite the importance of the incretin-mimetics for diabetes therapy, our understanding of GLP1R and GIPR expression patterns and signaling within the islet remain incomplete." (PMID 38360354, 2024). "In PC12 cells and rats models, we indicated that the expression of GLP-1R is downregulated in diabetes, which demonstrated that GLP-1R is a critical factor in diabetes cognitive dysfunction." (PMID 39257395, 2024). "Our results demonstrated that baicalein improves hyperglycemic, hyperinsulinemic, and glucometabolic disorders in mice with induced diabetes via GLP-1R." (PMID 39456499, 2024). "Early results of clinical trials of co-agonists of glucagon and its related receptors (GLP-1R and glucose-dependent insulinotropic peptide receptor) as treatments for MASLD are promising (American Diabetes Association 2023, Boehringer Ingelheim 2024)." (PMID 38579751, 2024). "Beyond diabetes and obesity, GLP-1R agonists exhibit a multifaceted impact on cancer progression across various malignancies." (PMID 38801466, 2024). "Given that diabetes is a known risk factor for both cardiac diseases and POD, GLP‐1R agonists emerge as a promising treatment option." (PMID 38155547, 2024). "Glucagon-like peptide-1 receptor agonists (GLP-1RAs) are a class of medications for management of diabetes and obesity." (PMID 38421490, 2024). "Injectable once-weekly semaglutide for diabetes (OW sema T2D) is a glucagon-like peptide-1 receptor agonist (GLP-1 RA) that has demonstrated considerable efficacy in improving glycemic control and promoting weight loss in patients with T2DM." (PMID 39507603, 2024). "Glucagon-like peptide-1 (GLP-1) is an incretin hormone, glucagon-like peptide-1 receptor (GLP-1R) agonists play an important role in the treatment of diabetes." (PMID 39257395, 2024). "Glucagon-like peptide-1 receptor agonists (GLP-1 RAs) have become one of the most popular medications for patients with diabetes and obesity." (PMID 39337114, 2024). "The improvement can likely be credited to the common use of certain diabetes drugs, like GLP-1R agonists and SGLT-2 inhibitors, which have been shown to greatly enhance heart health and reduce death rates." (PMID 38730476, 2024). "The activation of GLP-1 receptors (GLP-1R) plays protective roles against multiple neurodegenerative disorders, including Alzheimer’s disease and Parkinson’s disease, as well as diabetes mellitus and ischemia." (PMID 39301568, 2024). "Understanding the mechanism involved in appetite suppression following GLP‐1R agonism is of great significance, considering its increasing popularity as a treatment for both diabetes and obesity." (PMID 38965822, 2024). "In the present study, we focused on the effect of GLP-1R on oxidative stress and inflammation in diabetes cognitive dysfunction." (PMID 39257395, 2024). "Therapeutics based on GLP-1R as novel anti-diabetic drugs have been applied in the treatment of diabetes and obesity for decades." (PMID 39456499, 2024). "In summary, these data convincingly demonstrate that the chronic activation of the GLP1R prevents the development of adverse remodeling of the heart in myocardial infarction, hypertension, and diabetes." (PMID 38732142, 2024). "The frequency of diabetes medication use like sulfonylurea (p < 0.001), GLP-1r (p = 0.007), SGLT2i (p < 0.001), DDP4 (p < 0.01), and insulin (p < 0.001) also showed significant differences between clusters." (PMID 38472402, 2024). "GLP-1R agonist liraglutide significantly improved lipoatrophic diabetes and hepatic steatosis in mice with generalised lipodystrophy." (PMID 38745956, 2024). "Glucagon-like peptide-1 receptor agonists and sodium–glucose cotransporter 2 inhibitors both provide protection against progression of kidney disease in diabetes." (PMID 39078489, 2024). "Glucagon-like peptide-1 receptor agonists (GLP-1RAs) have been gaining popularity in managing diabetes mellitus (DM) owing to their effectiveness, cardioprotection, and convenient dosing." (PMID 39238749, 2024).
diabetes (continued). "There are in fact several GCGR/GLP-1R coagonists in development for the treatment of diabetes, obesity, and nonalcoholic steatohepatitis." (PMID 38681771, 2024). "GLP‐1R agonists are widely used in the treatment of diabetes and improve cognitive function by downregulating A1 astrocytes." (PMID 38155547, 2024). "In conclusion, our results indicate that baicalein improves the glucose metabolism of diabetes through ameliorating IR occurring in liver and skeletal muscle tissues with the existence of GLP-1R." (PMID 39456499, 2024). "Given the expanding clinical application of GLP-1R agonists for both diabetes management and weight control, clarifying their safety profile concerning electrolyte homeostasis is increasingly important." (PMID 39201039, 2024). "The newly created medication liraglutide, which is an analog of GLP-1R and designed for treating diabetes, presents a new way to address MS." (PMID 39429275, 2024). "In the current study, T2DM and VC mouse models were established, and the GLP-1R agonist exendin 4 (EX4) was used as a potential therapeutic agent for diabetes-related VC." (PMID 38720283, 2024). "Specifically, GLP-1R agonists (GLP-1RAs) like liraglutide and exenatide have shown significant clinical success in managing diabetes and its associated atherosclerotic complications." (PMID 39493783, 2024). "GLP1R agonists (GLP1RA) are widely used in the treatment of diabetes and obesity, yet visualizing the endogenous localization, organization and dynamics of a GPCR has so far remained out of reach." (PMID 36653347, 2023). "Other drugs, such as glucagon-like peptide-1 receptor agonists (GLP-1-RAs), have shown significant weight loss and a reduction in CV events in diabetics with obesity." (PMID 37176761, 2023). "A recent study has proposed that inhibition of the KATP channels by mutation or long-term use of sulfonylureas leads to persistently depolarised β-cells in diabetes and that GLP-1R switches coupling from Gs-to-Gq signalling to amplify insulin secretion." (PMID 36943057, 2023). "The recently approved glucagon-like peptide-1 receptor agonists (GLP1RA) have been groundbreaking in their ability to treat diabetes and obesity with a comparatively benign side effect profile." (PMID 38201269, 2023). "Combining the activation of the two receptors, greater improvement of β-cell function offers more effective treatment of diabetes and obesity with fewer adverse effects than selective GLP-1R agonists." (PMID 36909312, 2023). "Butyricimonas can activate glucagon-like peptide-1 receptor and peroxisome proliferator-activated receptor α, which can alleviate diabetes and metabolic disorders induced by a high-fat diet." (PMID 37630576, 2023). "The glucagon‐like peptide‐1 receptor (GLP‐1R) agonists have shown great potential in treating diabetes mellitus, neurodegenerative diseases, obesity and hypertension." (PMID 36528874, 2023). "The glucagon-like peptide-1 receptor (GLP-1R) is a validated target for the treatment of diabetes and obesity, but drugs that target this receptor are a frequent cause of adverse events." (PMID 37813859, 2023). "Prolonged administration of the glucagon like peptide 1 receptor (GLP1-R) agonists have demonstrated beneficial effects in preventing diabetes, excitotoxicity, and ER stress in aged rats and delaying disease progression." (PMID 36645345, 2023). "Tirzepatide was the first dual GIP/GLP-1R agonist to be approved for the treatment of diabetes in the United States as a novel glucose-lowering medication." (PMID 37096236, 2023). "In particular, glucagon-like peptide-1 receptor agonists (GLP-1RAs) have profoundly shifted the diabetes treatment paradigm." (PMID 37492314, 2023). "The most common keywords used in the most recent research papers are semaglutide, obesity, T2DM, diabetes mellitus type 2 and glucagon-like peptide-1, glucagon-like peptide-1 receptor agonist, antidiabetic agent, liraglutide, and cardiovascular disease." (PMID 37808605, 2023).
diabetes (continued). "As diabetes is a leading cause of CKD, new therapies with glucagon-like peptide-1 receptor agonists (GLP-1-RA) and sodium/glucose cotransporter 2 inhibitors (SGLT2i) showed antihyperglycemic effect, and reduced all-cause mortality and CV mortality." (PMID 37908502, 2023). "Compared to the therapeutic limitations of insulinoma, quantifying BCM and treating diabetes through GLP-1R molecular imaging have shed light on theranostics." (PMID 37780209, 2023). "While GLP-1R agonists are well established for the treatment of hyperglycemia in the context of diabetes, GLP-1R antagonists are nowadays in the focus to fight hypoglycemia." (PMID 36769142, 2023). "Here, we confirmed that the long-acting GLP-1R agonist dulaglutide also prevents and reverses glucose intolerance/diabetes in Wfs1 KO mice by enhancing beta cell function." (PMID 36995380, 2023). "Our work aids in dissociating the neural substrates that mediate the anorectic effects from those that contribute to the feeling of illness following either endogenous GLP-1R signaling or delivery of GLP-1R agonists for obesity and diabetes treatment." (PMID 37729419, 2023). "Decreased expression of GLP-1R has been reported in pancreatic β cells of diabetes and pancreatic cancer tissues." (PMID 37370018, 2023). "In recent years, tirzepatide has become the first dual GIP/GLP-1R agonist approved for the treatment of diabetes mellitus in the United States as a new hypoglycemic medicine." (PMID 37096236, 2023). "The introduction of GLP-1-R agonists is also substantiated by The Diabetes, Cardiorenal, and Metabolism task force, which considers such drugs to be effective in primary and secondary stroke prevention in subjects with T2DM." (PMID 37623335, 2023). "Emerging therapies, such as sodium-glucose co-transporter-2 inhibitors and glucagon-like peptide-1 receptor agonists, have shown promising results in reducing cardiovascular events, hospitalizations, and mortality in patients with HF and diabetes." (PMID 37713837, 2023). "The strong association between GLP-1R gene polymorphisms and the hypoglycemic effects of DPP-4 inhibitors and GLP-1RAs makes the GLP-1R gene a candidate gene for precision medicine in diabetes." (PMID 36528605, 2022). "Several studies investigated GLP1R polymorphisms related to glucose levels and insulin secretion and the pathogenesis of obesity and T2DM diabetes." (PMID 35408810, 2022). "Examples of glucagon-like peptide-1 receptor agonists approved by the FDA for diabetes (some of which are also approved for obesity) are liraglutide, exenatide, lixisenatide, dulaglutide, semaglutide, and albiglutide." (PMID 36013401, 2022). "Diabetes is commonly treated with glucagon-like peptide-1 receptor (GLP-1R) agonists including liraglutide and others." (PMID 35890201, 2022). "Glucagon-like peptide-1 receptor (GLP-1R) agonists, widely used in the treatment of diabetes, are reported to exert neuroprotective effects in the central nervous system." (PMID 36615696, 2022). "Two conventional small molecule agonist with agonism at GLP-1R have recently been disclosed and are in clinical evaluation for the oral treatment of diabetes." (PMID 35299971, 2022). "Sodium-glucose cotransporter-2 inhibitors (SGLT2i) and glucagon-like peptide-1 receptor agonists (GLP-1RA) have shown benefits in patients with diabetes and cardiovascular disease (CVD), heart failure (HF), and chronic kidney disease (CKD)." (PMID 35606699, 2022). "We report for the first time the results of the use of combination therapy with a glucagon-like peptide-1 receptor agonist and a sodium-glucose cotransporter 2 inhibitor for the treatment of diabetes in the context of type A IR syndrome." (PMID 35498407, 2022). "Currently, two different injectable therapies are available for diabetes, one is insulin and the other is glucagon-like peptide-1 receptor agonist (GLP-1 RA), which is a relatively new class of glucose-lowering medications." (PMID 36559020, 2022).
diabetes (continued). "GLP-1 controls glucose metabolism and energy homeostasis by regulating food intake, islet hormone secretion and gastrointestinal motility via GLP-1 receptor (GLP-1R), enabling the development of GLP-1R agonists for the treatment of diabetes and obesity." (PMID 36497087, 2022). "Recently, interest has been shown in glucagon-like peptide-1 receptor (GLP-1R) agonists, a class of medication increasingly used for diabetes control, as a potential treatment for smoking cessation." (PMID 36293800, 2022). "The glucagon-like peptide-1 receptor (GLP-1R) can be targeted in the treatment of diabetes, obesity and other metabolic disorders." (PMID 35013280, 2022). "It has been discovered that in vivo deletion of miR-204 is protective against diabetes by increasing GLP-1R and insulin secretion." (PMID 36422510, 2022). "Several randomized controlled trials have demonstrated the benefits of glucagon-like peptide-1 receptor agonists (GLP-1RAs) on ischemic stroke in patients with diabetes." (PMID 36380358, 2022). "Although GLP-1R agonists have been used for the treatment of diabetes, their efficacy is limited by target receptor desensitization and downregulation via the recruitment of β-arrestins." (PMID 35784565, 2022). "Currently, various GLP‐1R agonists approved for the treatment of diabetes also stimulate cardiovascular benefits in some populations." (PMID 35166002, 2022). "Several GLP-1 receptor agonists have now been approved for the treatment of diabetes and/or obesity, and the anorectic effects of GLP-1, although pleiotropic, are increasingly linked to agonism of the GLP-1 receptor (GLP-1R) in multiple brain regions." (PMID 35474339, 2022). "Multiple linear regression analysis revealed that PDR remained independently and negatively associated with GLP-1R protein level and SGLT2 mRNA level after adjustment for age, gender, BMI, diabetes duration, FPG and HbAlc (P=0.003 and P=0.028, respectively)." (PMID 36465606, 2022). "Targeting of glucagon‐like peptide 1 receptor (GLP‐1R), expressed on the surface of pancreatic β‐cells, is of great interest for the development of advanced therapies for diabetes and diagnostics for insulinoma." (PMID 35762648, 2022). "This study proves the superiority of glucagon-like peptide-1 receptor agonist medications in treating diabetes mellitus, obstructive sleep apnea, and obesity at the same time." (PMID 36013401, 2022). "The glucagon-like peptide-1 receptor (GLP-1R) plays a key role in metabolism and is an important therapeutic target in diabetes and obesity." (PMID 36010663, 2022). "This review focuses on the recent advances in non-invasive in vivo β-cell imaging and BCM evaluation for type 1 and type 2 diabetes mellitus, especially exendin-based GLP-1R-targeted nuclear medicine techniques." (PMID 34248856, 2021). "Incretin therapy for diabetes control is based on GLP-1R agonists and DPP-4i whose glycemic effects are mediated by these receptors." (PMID 34471642, 2021). "With regards to diabetes, it is now well established that chronic administration of GLP-1R mimetics not only enhances insulin secretion but also positively influences overall islet function, restoring normal morphology in even severe models of diabetes." (PMID 34093449, 2021). "In recent years, GLP-1R agonists have been shown to be effective and safe treatments for diabetes and diabetic complications." (PMID 34938383, 2021). "In order to research the possible target of LB in the treatment of diabetes, molecular docking was used to simulate the interaction between LB and potential targets, and among them, glucagon‐like peptide‐1 receptor (GLP‐1R) had the optimal results." (PMID 33300675, 2021). "Glucagon-like peptide-1 receptor agonists (GLP-1 RAs) are a class of medications utilized for the treatment of diabetes mellitus by mechanisms promoting incretin release and insulin production." (PMID 34336446, 2021).